AKT1 (AKT serine/threonine kinase 1)
Diseases named in the same sentence as AKT1 in open-access papers (continued):
Sharing a sentence is not in itself a finding about the gene and the disease.
infection (147 papers, 2005 to 2026). The state of being infected such as from the introduction of a foreign agent such as serum, vaccine, antigenic substance or organism. "We found Cbl and Akt1, two genes implicated in the mTOR signaling pathway to be upregulated in every subset from the bone marrow and spleen in response to the secondary infection." (PMID 34975887, 2021). "In addition, cells deficient in AKT1 or AKT2 were more resistant to LGTV-induced cell death due to higher amounts of pAKT at a late stage in infection." (PMID 32977414, 2020). "Indeed, akt-1 (mg144) mutants carrying gain-of-function mutations in the PI3K kinase suppressed the infection phenotype conferred by lin-7 RNAi treatment (P < 0.0001)." (PMID 22672310, 2012). "triangularis infection-related proteins, highlighting hub genes such as AKT1, TNF, MMP9, CDK1, and PIK3C3, and enriched pathways in autophagy, immune regulation, oxidative stress responses, and kinase-mediated signaling." (PMID 41993607, 2026). "In 3D4/21 cells, with increasing NS5A infection time, the protein expression of AKT1, IKBKG, CDC37, MAP3K2, and PKN2 decreased, whereas the protein expression of KRAS2 and MAP3K7 increased." (PMID 40078537, 2025). "We verified that overexpression of AKT1 by infection with the constitutively active (CA)-AKT1 adenovirus containing an src myristoylation sequence and a GFP-tag, completely inhibited TG- and TU-induced c-Cas-3 expression in both WT and GRP94 KD cells." (PMID 38811543, 2024). "In the post-infection phase at three and ten months, there was persistent protein underexpression of pathways essential for cellular function, signaling, and homeostasis (AKT1, MAPK14, HSPB1)." (PMID 39324144, 2024). "In agreement with the reduced protein abundance of AKT1 after MPXV infection, AKT1-regulated sites were less phosphorylated over the course of the infection, e.g., IRS1 pS629, PDCD4 pS457." (PMID 39117661, 2024). "The importance of potassium in defense is further underlined by the fact that the rice blast pathogen Magnaporthe oryzae targets the AKT1 potassium channel using the AvrPiz-t effector to promote virulence during infection." (PMID 36035673, 2022). "We showed that the expression of ITGA5, p-FAK, p-P85, and p-Akt1 was dramatically decreased following sh-ABHD11-AS1 infection in two CRC cell lines." (PMID 34375304, 2021). "The two main modes of Attacin production, including the induced (by a factor of even > 100) upon infection mode, and the basal in absence-of-infection mode link immunity with the Akt1/foxo IIS metabolic signaling pathway." (PMID 33193649, 2020). "Infection of cells with EBOV results in the activation of the PI3K/AKT pathway as demonstrated by the phosphorylation of AKT1." (PMID 33052961, 2020). "Phosphorylation of HER2 as well as AKT1 by EBOVΔVP30 was detected at 30 min post-infection in Huh7.0 cells transfected with a control siRNA (all panels)." (PMID 33052961, 2020). "Both Akt1 and Akt2 were demonstrated to phosphorylate PDK1, and PDK4 expression was markedly inhibited by infection with shRNA directed against Akt1." (PMID 31398213, 2019). "Transient expression of OIP5 by infection with Ad-OIP5 also increased the phosphorylation of AKT1 and AKT2 in HLK3 and SH-J1 cells." (PMID 28184024, 2017). "Infection with Ad-E1A12 or viruses with mutant E1A12 moderately increased AKT1 pS473 levels at 24hpi." (PMID 27849011, 2016). "Akt-1 is absolutely required for the infection and its inhibition completely eliminated expression of T-ag." (PMID 27462916, 2016). "Compared to the parental cells, infection of the MDA-MB-231 cells with miR-200 expression with Ad-E1A12 or a virus with a mutant E1A12 attenuated AKT1 phosphorylation and markedly suppressed S6 phosphorylation." (PMID 27849011, 2016). "Knockdown of XBP1 via shRNA lentiviral infection not only abolished flow-induced but also decreased the basal level of Akt1 phosphorylation and HO-1 expression." (PMID 25190803, 2014).
infection (continued). "To genetically confirm the role of various AKT isoforms in macrophage infection, we knocked down the expression of AKT1, AKT2, and AKT3 in J774 macrophages." (PMID 24586159, 2014). "Wild type and Akt1 null animals were subjected to cutaneous wound healing, followed by infection with Staphylococcus aureus." (PMID 21559496, 2011). "Indeed, post-infection time-course RNA-seq analysis showed an upregulation of Casp3 but also a number of other genes involved in apoptosis and necroptosis such as Stk24, Akt1, Madd, Casp7, and Casp8 peaking at 5 and 6 dpi." (PMID 38009950, 2024). "We also discovered that cells individually lacking AKT1 or AKT2 survive LGTV infection better than WT cells, and this was associated with higher amounts of antiapoptotic XIAP and survivin and increased resistance to LGTV-induced apoptotic cell death." (PMID 32977414, 2020). "In addition, in the total cell extract, EBOVΔVP30-induced AKT1 phosphorylation was appreciably impaired after infection in HER2 siRNA-treated cells compared to control siRNA-treated cells." (PMID 33052961, 2020). "We found collectively among SP-A variants several genes such as AKT1, BTK, CCL9, PPARG, and RELA to exhibit higher expression in females, whereas, CFLAR, C1QC, LSP1, CKAP2, KAT2B, TACC2, and RCC2 exhibited higher expression in males after infection." (PMID 32670284, 2020). "Consequently, we observed a greater reduction to the number of attached, viable ESCs by combined Akt1/3 knockdown than by depleting Akt3 only at 3 and 6 days after lentiviral shRNA infection." (PMID 28483982, 2017). "We investigated whether mutant AKT1-E17K transforms lung epithelial cells using human normal bronchial epithelial cells immortalized by infection with Adenovirus 12/SV40 hybrid virus (BEAS-2B)." (PMID 26053093, 2015). "Total cell lysates prepared from mouse lungs at 12, 20 and 32 weeks post-infection with AJEJJenv were probed by western blot with antibodies against Akt1, Akt2 and Akt3 to determine whether Akt isoform expression levels varied relative to normal lung." (PMID 24722238, 2014). "Notably, the PI3K / Akt1 pathway appeared specifically down-regulated following Schu S4 infection and a concomitantly lower cytokine response was observed." (PMID 18698339, 2008). "The level of Akt1 protein starts to increase at 3 hours post infection." (PMID 18714386, 2008). "In this HBV mouse model, HBV virions produced from the AdHBV infection in hepatocytes were unable to infect surrounding hepatocytes due to the limitation of host range, confirming the strong intrahepatic cytotoxic capability of Akt1-OE CTLs on one-round Ag stimulation." (PMID 40139836, 2025). "In addition, LGTV-infected AKT1 KO and AKT2 KO cells had higher levels of either AKT2 or AKT1, respectively, than WT cells, further suggesting that depletion of one of these isoforms causes a decrease in pAKT during infection." (PMID 32977414, 2020). "With increasing infection time, the expression levels of IKBKG and KRAS2 increased, whereas the expression levels of MAP3K7, MAP3K2, AKT1, CDC37, and PKN2 decreased." (PMID 40078537, 2025). "The results revealed that with increasing infection time, the expression of IKBKG, AKT1, CDC37, MAP3K2, and PKN2 decreased, whereas the expression of MAP3K7 and KRAS2 increased." (PMID 40078537, 2025). "In the present study, AKT1 was upregulated and TIMP3 downregulated at 48 hpi to various degrees following MDV and REV coinfection comparison to a single infection." (PMID 35392111, 2022). "We next analyzed the protein-protein interaction network even further and demonstrated that the infection related proteins STAT3, AKT1, MAPK9, MAPK14, and CREBBP had the highest degree of connectivity among DAPs." (PMID 36262184, 2022).
infection (continued). "Silencing of PDPK1, Akt1, or PLCγ resulted in a reduction in VSV-S infection supporting the importance of this signaling pathway." (PMID 36245045, 2022). "The expression levels of ITGA1, ITGA5, FAK, PIK3R1, PIK3CA and AKT1 were significantly higher in the 1 MOI L. salivarius-treated group, than in untreated cells at 2, 8, and 16 h post-PEDV infection." (PMID 34957282, 2021). "We found that AKT1 and AKT2 were downregulated at the protein level during the acute phase of infection, but AKT3 was upregulated." (PMID 32977414, 2020). "We observed that AKT1 and AKT2 levels decrease over time as infection progressed, but AKT3 was dramatically increased at 120 hpi." (PMID 32977414, 2020). "Surprisingly, we found that AKT1 KO and AKT2 KO cells survived the acute phase of infection in greater numbers compared to the WT cells." (PMID 32977414, 2020). "If the lin-7-mediated infection phenotype involves DAF-2 signalling, then the enhanced survival exhibited by lin-7 mutants should also be abolished by constitutively activating AKT-1, the PI3K kinase downstream of DAF-2." (PMID 22672310, 2012). "We have found that SV40 activates Akt-1 survival pathway and the Hsp/c70 chaperones via PLC-γ signaling (unpublished results), very early post infection." (PMID 18714386, 2008). "Also, the STAT3, AKT1, MAPK9, MAPK14, and CREBBP were identified as host’s infection response regulators of bacterial Hcp in duck." (PMID 36262184, 2022). "Here, we showed that HER2 is also phosphorylated during EBOVΔVP30 infection, and the downstream phosphorylation of AKT1 during infection is dependent on HER2, and not the other RTKs we evaluated." (PMID 33052961, 2020). "AKT1 and AKT2 levels decreased as infection progressed, compared to the mock infected cells." (PMID 32977414, 2020). "Although the infection does not change the expression levels of Akt1 and Akt2 mRNA and proteins, the phosphorylated forms of these proteins are upregulated in the heart tissue of infected mice compared to the uninfected group." (PMID 29666415, 2018). "Taken together, these data indicate that the canonical PI3K-AKT-mTOR signaling pathway is constitutively active in epithelial cancer cells and that this pathway cannot be sustained, when AKT1 and other proteins critically involved in cell survival are degraded upon Ad-E1A12 infection." (PMID 27849011, 2016). "Moreover, kinases found to be upregulated by the infection of HIBCPP cells with both N. meningitidis strains in this analysis (downregulated in control cells) include MAPKAPK2, RPS6KB1, RET as well as AKT1 and AKT2, whereas PRKACA activity was upregulated only by MC58siaD." (PMID 37065199, 2023). "The female mice exhibited higher expression levels of AKT1, BTK, CCL9, and LSP1 (KO, 1A0), PPARG (KO, 1A0, and 6A2), CFLAR, and ERP44 (1A0, 6A4), CCL9 (KO, 1A0, and 6A4), RCC2, and RELA (KO), KAT2B (6A2) and FKBP5 (1A0, 6A2, and 6A4) compared to males in response to infection." (PMID 32670284, 2020). "However, in response to infection, male mice exhibited higher expression levels of CFLAR, and FKBP5 (KO, 1A3), AKT1, and CCL9 (1A3, 6A2), C1QC (6A2), LSP1 (1A3, 6A2, and 6A4), CKAP2, and KAT2B (KO), TACC2 (1A0), RCC2 (1A3, 6A2), PPARG (1A3, 6A4), and ERP44 (6A2) compared to females." (PMID 32670284, 2020). "By 32 weeks post-infection, small and medium sized tumors were detectable in only one of five Akt1−/− mice and while Akt3−/− mice had greater numbers of large tumors (>300 μm) compared to WT and Akt1−/− mice, this was not statistically significant." (PMID 24722238, 2014). "Silencing of PDPK1, Akt1 and PLCγ1 resulted in significant reduction of VSV-S but not VSV-G infection." (PMID 36245045, 2022). "In presence of constitutively active AKT1 (HA-AKT1DD), Wt-β-catenin was phosphorylated even in absence of infection, as evidenced by high-band intensity (lane 4)." (PMID 30770800, 2019).
metabolic disorders (54 papers, 2015 to 2026). "Abnormal AKT1 signaling can cause metabolic disorders in pancreatic acinar cells, making pancreatic cells more sensitive to damaging factors such as abnormal activation of trypsinogen and oxidative stress." (PMID 39771144, 2024). "In general, AKT1 plays a crucial role in glucose and lipid metabolism and thus is a promising therapeutic target for metabolic diseases." (PMID 35811658, 2022). "GM dysbiosis and inflammation also induce epigenetic alterations in cytokine genes, such as IL-1β, IL-6, TNF-α, NF-kB, BTLA, IL-18R1, TGF-β, P13k/Akt1, Ctnnb1, and Hsp90aa1, as well as DNMTs, HDACs, and DAT1 associated with the development and progression of metabolic disorders and/or NPDs." (PMID 41228440, 2025). "The current study is the first to demonstrate that ECG can improve metabolic disorder by inhibiting inflammatory responses and NLRP3 inflammasome activation as well as modulating the PI3K/AKT1 signaling pathway." (PMID 41169786, 2025). "Consequently, the dynamic response of Akt1 to fructose and the divergence in its downstream metabolic routing fundamentally stem from the unique biochemical metabolic route of fructose, underscoring its central and specific role in fructose-related metabolic diseases." (PMID 41415834, 2025). "Through SELENOF and AKT1/FOXO3a/PYGL, selenium-containing agents regulate glucose and lipid homeostasis in the liver, preventing metabolic disorders." (PMID 35743086, 2022).
neurodegenerative disease (48 papers, 2009 to 2026). A disorder of the central nervous system characterized by gradual and progressive loss of neural tissue and neurologic function. "The PI3K/AKT1 pathway plays an important role in the cellular oxidation process and contributes to the pathophysiology of neurodegenerative diseases." (PMID 33289908, 2021). "Neuroprotective effects were observed after AKT1 kinase activity was enhanced, and pAKT1 was upregulated in cellular and animal models of neurodegenerative diseases." (PMID 31936558, 2020). "Based on the longevity-related genes (i.e., Akt1, NRF1, parkin, and AIMP2), potentially effective therapeutics might be exploited for the rejuvenation and cure of age-associated neurodegenerative diseases." (PMID 36711211, 2022). "The over-representation of neurodegenerative disease-associated genes and processes in the HLHS interactome should be investigated, with a focus on the potentially pleiotropic roles of the AKT1-mediated pathways and the intrinsic apoptotic pathway in HLHS and neurodegeneration." (PMID 35456433, 2022). "Comparatively, our findings are consistent with existing literature indicating the crucial roles of AKT1 and PPARGC1A in neurodegenerative diseases." (PMID 40642087, 2025).
cardiovascular disease (38 papers, 2008 to 2025). "We herein demonstrate that Akt1-directed eNOS activation indeed serves an athero-protective role, where we further substantiate the Akt1-eNOS axis as the major signaling mechanism that links endothelial integrity to cardiovascular disease outcome." (PMID 38034389, 2023). "Another typical example is circ-AMOTL1, which directly binds to PDK1 and AKT1, leading to AKT1 phosphorylation and nuclear translocation, and plays a cardio-protective role in cardiovascular disease." (PMID 36338714, 2022). "Many studies have suggested that Akt1 has a protective effect in cardiovascular disease, but some studies still disagree." (PMID 35287352, 2022). "Their study suggested the method of UTMD-assisted exogenous Akt1 gene transfection had a chance to be applied to gene therapy of cardiovascular disease." (PMID 24900995, 2014). "In addition, FYN and AKT1 are shown to be pivotal with angiogenic functions and the relation to cardiovascular disease." (PMID 30717456, 2019). "Akt1 regulates platelet aggregation and spreading, which may also contribute to cardiovascular disease." (PMID 30444896, 2018). "Thus Akt1 plays both positive and negative regulatory roles in cardiovascular disease." (PMID 30444896, 2018). "Furthermore, Akt1 but not Akt2 in ECs uniquely phosphorylates protein substrates implicated in cardiovascular disease, including FOXOs and eNOS." (PMID 25929188, 2015). "Among the three isoforms, AKT1 is most closely related to cardiovascular disease because AKT1, not AKT2, is critical for ischemic and vascular endothelial growth factor-mediated angiogenesis." (PMID 35111368, 2022).
prostate (33 papers, 2011 to 2025). "Lastly, we found recurrent, E17K AKT1 oncogenic mutations in multiple lung cylindromas in each patient, and in both patients independently as well." (PMID 31624251, 2019). "Deletion of Akt1 enhanced splenic egress and lung recruitment of α7 nAChR+CD11b+ cells, which elicited neutrophil-infiltrated lung inflammation and injury." (PMID 28529765, 2017). "In other words, our murine models could not preserve the skeletal musculature by systemic Akt1 KO; thus, this skeletal loss by Akt1 KO could contribute to kidney injuries including fibrosis and apoptosis." (PMID 33299873, 2020).
neurological disorders (32 papers, 2009 to 2026). "AKT1 has been linked to dopamine-related neurological diseases because it influences dopamine-related behaviors and participates in the dopamine signaling pathway." (PMID 41601963, 2026). "Akt1 is well known for its role in regulating cell proliferation, differentiation, and apoptosis and is implicated in tumors and several neurological disorders." (PMID 23342113, 2013). "The selective expression of AKT1 in interneurons suggests an essential role for this isoform in interneuronal function and, therefore, in neurological disorders with E/I imbalances." (PMID 34296180, 2021). "Akt1 serves as the principal effector within the phosphoinositide 3-kinase (PI3K)-Akt signaling pathway, and the absence of Akt1 kinase activity has been associated with the onset of neurological disorders." (PMID 40520679, 2025). "The study shows that proteins (SOX2, STAT1, AKT1, and CTNNB1) can be used as markers for neurological disease at the early stage of neuronal development, and they can be potential drug targets for therapeutic development." (PMID 30598663, 2018).
adenocarcinoma (26 papers, 2010 to 2025). A common cancer characterized by the presence of malignant glandular cells. "There was increased nuclear signal in Pten/Rb-null adenocarcinomas (bottom), consistent with a previous report of localization of AKT1 in the cytoplasm and AKT2 in the nucleus of PC-3 cells." (PMID 37292818, 2023). "Fifty percent of adenocarcinomas with clear cell component (11/22) harbored EGFR mutation, 41 percent (9/22) harbored KRAS mutation and 5 percent (1/22) harbored AKT1 mutation." (PMID 27013585, 2016). "Supporting its role in lineage plasticity, N-Myc overexpression, combined with activated AKT serine/threonine kinase 1 (AKT) or PTEN loss, induces invasive tumors with adenocarcinoma, NEPC, mixed or aberrant phenotypes with a prevalence of NEPC after prolonged castration." (PMID 38398199, 2024). "Furthermore, the activation of the PI3K/AKT1 and ASCL1 signal transduction pathways was shown to be associated with the transformation of adenocarcinoma to SCLC." (PMID 35806042, 2022). "Matched trial therapies were available for 20% (3/15) of patients with adenocarcinoma (NOS), 13% (2/15) to AKT1 inhibitors (NCT01226316, NCT02338622) and 7% (1/15) to RAF/MEK inhibitors, based on a KRAS mutation through NCT02407509." (PMID 35267442, 2022). "Consequently, the gene silencing and/or drug‐dependent inhibition of the MR kinases AKT1, CDK1&2, ERBB2 and the downstream kinase EGFR markedly reduced cell viability in a large panel of human adenocarcinoma cell lines." (PMID 39995112, 2025). "In addition, the SCLC component may derive from the adenocarcinoma component through the activation of achaete-scute family bHLH transcription factor 1 (ASCL1) and PI3K/AKT1 signal transduction pathways." (PMID 35806042, 2022).
heart disease (13 papers, 2008 to 2024). "It remains unclear whether mutations in Akt1 gene play a role in human cardiac disease." (PMID 24400145, 2013).